EPHX1 (epoxide hydrolase 1)
Diseases named in the same sentence as EPHX1 in open-access papers (continued):
Sharing a sentence is not in itself a finding about the gene and the disease.
polycystic ovary syndrome (4 papers, 2014 to 2021). A disorder that manifests as multiple cysts on the ovaries. "A study on epigenetic factors revealed that the methylation level of the EPHX1 promoter was significantly lower in patients with polycystic ovary syndrome than in controls, consistent with a role of EPHX1 in steroidogenesis." (PMID 33374956, 2020). "Polycystic ovary syndrome, characterized by hyperandrogenism and elevated serum testosterone levels, is observed in patients taking sodium valproate, an anti-epileptic and anti-convulsant drug known to inhibit EPHX1 activity." (PMID 34342583, 2021).
Alzheimer disease (3 papers, 2017 to 2025). A progressive, neurodegenerative disease characterized by loss of function and death of nerve cells in several areas of the brain leading to loss of cognitive function such as memory and language. "Further evidence for its role in neurodegeneration comes from a study reporting increased EPHX1 expression in the brains of patients with Alzheimer’s disease." (PMID 41007636, 2025). "Abnormalities in Ephx1 expression are involved in neurological disorders such as Alzheimer’s disease and tumours." (PMID 29867349, 2018). "The dysfunction of EPHX1 was reported to contribute to several human diseases, including neurodegeneration where its differential expression was presented in patients with Alzheimer’s disease." (PMID 28286461, 2017).
emphysema (3 papers, 2007 to 2016). "Upper lung-dominant emphysema is associated with genetic variants in MMP-9 or EPHX1 and GSTP1 and the cranial-caudal emphysema distribution is a powerful predictor of the response to lung volume reduction surgery." (PMID 22512922, 2012). "Previous studies have shown that variants of MMP-9 or EPHX1 and GSTP1 are associated with upper-predominant emphysema." (PMID 22512922, 2012). "Additional SNPs in these two genes, including a promoter SNP in EPHX1, appeared to have stronger effects in patients with upper lobe predominant emphysema and low baseline exercise tolerance." (PMID 17686149, 2007). "The significant genotype-phenotype associations for SNPs in GSTP1 and EPHX1 were further evaluated in four clinically-defined subgroups of patients in NETT, based on emphysema distribution and baseline exercise capacity." (PMID 17686149, 2007). "In the NETT Genetics Ancillary Study, we were able to identify variants in two genes, GSTP1 and EPHX1, which may predict outcome from LVRS, even when accounting for clinically-defined subgroups based on radiographic emphysema distribution and baseline exercise capacity." (PMID 17686149, 2007). "Analysis of SNPs in EPHX1 in all lung volume reduction surgery subjects (significant at p < 0.05) and in 4 subgroups defined by NETT based on upper lobe predominant emphysema on chest CT (upper lobe predominant vs. non-upper lobe predominant) and baseline exercise capacity (low vs. high)." (PMID 17686149, 2007).
Obesity (3 papers, 2024 to 2025). Accumulation of substantial excess body fat. "This increase was not linked to changes in hepatic mRNA levels of EPHX1 and EPHX2 as both microsomal and soluble isoforms' expression were not significantly altered with T2DM in patients with obesity." (PMID 38677183, 2024). "Despite the known involvement of EPHX1 in the bioactivation of DMBA, neither DMBA nor HFHS-induced obesity impacted ovarian EPHX1 protein levels in contrast to a study in which exposure to DMBA for 14 d increased ovarian EPHX1 protein in ovaries of 20-wk-old lean and hyperphagia-induced obese mice." (PMID 39910959, 2025).
adenoma (2 papers, 2007 to 2013). A neoplasm arising from the epithelium. "For the high-risk adenomas this positive association was more obvious for the common allele (Tyr allele) of the EPHX1 codon 113 polymorphism." (PMID 18093316, 2007). "The most convincing evidence of a modifying effect by genotype on dietary exposure was found between EPHX1 codon 113 in adenomas and EPHX1 codon 139 in carcinomas." (PMID 18093316, 2007). "The same was seen for the EPHX1 codon 113 polymorphism in the low-risk adenomas, although not so obvious." (PMID 18093316, 2007). "An association was also observed for the EPHX1 codon 113 polymorphism in the low-risk adenomas, although not as obvious." (PMID 18093316, 2007).
allergic asthma (2 papers, 2014 to 2016). A asthma with a basis in a pathological type I hypersensitivity reaction. "The EPHX1 Y113H and IL5 C-703T SNPs had a moderate antagonistic effect on the allergic asthma risk in women." (PMID 24895604, 2014).
childhood asthma (2 papers, 2012 to 2025). "Discuss the correlation between single nucleotide polymorphisms (SNPs) of the Glutathione s-transferase Pi-1 (GSTP1), Catalase (CAT), Heme oxygenase-1 (HMOX1), and Homo sapiens epoxide hydrolase 1 (EPHX1) genes and the risk of childhood asthma in Fuzhou." (PMID 40433469, 2025). "To date, there is no research on the association between GSTP1, CAT, HMOX1, EPHX1 gene SNPs and the risk of childhood asthma in the Fuzhou region." (PMID 40433469, 2025). "Moreover, the IL4Ra and INSIG2 gene combination interacted with GSTP1, STAT6, ADRB2, ADRB3, IL13 and EPHX1 exon 3 to reveal a high training-balanced accuracy above 58.38% in childhood asthma." (PMID 22355322, 2012).
cholestasis (2 papers, 2013 to 2021). Impairment of the bile flow caused by obstruction within the liver, or outside the liver in the bile duct system. "Cancer and/or non-alcoholicfatty liver disease-related cirrhosis showed larger deteriorationin levels of CYP3A4, 2C8, 2E1, 1A6, UGT2B4/7, CES1, FMO3/5, EPHX1,MGST1/3, BSEP, and OATP2B1 than the cholestasis set." (PMID 34428046, 2021).
diabetes (2 papers, 2021 to 2025). "The involvement of the EPHX1 de novo variants identified herein in diabetes and liver dysfunction is also consistent with a number of previous observations." (PMID 34342583, 2021). "We identified two de novo variants located in EPHX1 catalytic site in patients with a lipoatrophic diabetes characterized by loss of adipose tissue, insulin resistance, and multiple organ dysfunction." (PMID 34342583, 2021). "A previous study also showed that a common polymorphism in EPHX1 (p.Tyr113His) was associated with an increased risk of type 2 diabetes mellitus and insulin resistance, as well as liver cirrhosis." (PMID 34342583, 2021). "Firstly, the expression of EPHX1 is regulated by various transcriptional factors including GATA4 and HNF4A, two genes implicated in other forms of monogenic diabetes." (PMID 34342583, 2021).
endometriosis (2 papers, 2020 to 2023). The growth of functional endometrial tissue in anatomic sites outside the uterine body. "Studies have revealed that certain genetic variations associated with endometriosis could influence the expression or enzymatic activity of EPHX1, thereby affecting the balance of estrogen metabolism and inflammatory responses." (PMID 38098472, 2023). "Repeated genes associated with P-phase (ACTB, ANXA4, BPIFB1, EPHX1, MUC5B, PRDX2, and VIM) could indicate stronger genetic causes associated with pathophysiology of endometriosis." (PMID 32474803, 2020). "The function of the EPHX1 gene might be related to the pathogenesis of endometriosis." (PMID 38098472, 2023). "Numerous studies based on cell or animal models have confirmed that FOS1, EPHX1, and PCSK5 have significant effects on the occurrence and development of endometriosis, which is consistent with the results of this study." (PMID 38098472, 2023).
head and neck cancer (2 papers, 2015 to 2025). A primary or metastatic malignant neoplasm affecting the head and neck. "In head and neck cancer-only cohort, TC genotype of EPHX1 rs1051740 was significantly associated with an increased risk of AKD in co-dominant [OR 13.333, 95% CI 1.684–105.533, P = 0.014] and over-dominant models [OR 4.029, 95% CI 1.552–10.455, P = 0.004]." (PMID 40526606, 2025). "Quantitative analyses of the EPHX1 His139Arg polymorphism on the head and neck cancer risk." (PMID 25923690, 2015). "Quantitative analyses of the EPHX1 Tyr113His polymorphism on the head and neck cancer risk." (PMID 25923690, 2015).
male infertility (2 papers, 2017 to 2024). The inability of the male to effect fertilization of an ovum after a specified period of unprotected intercourse. "Furthermore, the ICSI-associated DEGs MAP1B, HBA1, EPHX1, HBB, and HBG2 enriched in response-to-toxic-substance pathway are also interesting (FDR-corrected q-value < 0.05), considering that environmental exposures have been associated with male infertility in previous studies." (PMID 39702541, 2024).
prostate carcinoma (2 papers, 2021 to 2024). A carcinoma that arises from epithelial cells of the prostate gland. "EPHX1 overexpression is noted in castration-resistant prostate cancer." (PMID 38534761, 2024).
skin cancer (2 papers, 2015 to 2020). "In the univariate analysis, GSTT1 genotype, EPHX1 Tyr113His, and XPD C156A polymorphisms showed significant differences between skin cancer patients and controls." (PMID 26295053, 2015). "Individuals carrying three risk polymorphisms of EPHX1 Tyr113His, XPD C156A, and GSTs presented a 400% increased skin cancer risk when compared to those with less than or equal to one polymorphism." (PMID 26295053, 2015). "EPHX1 Tyr113His, XPD C156A, and GSTT1 null genotypes were associated with skin cancer risk (OR = 2.99, 95% CI = 1.01–8.83; OR = 2.04, 95% CI = 0.99–4.27; OR = 1.74, 95% CI = 1.00–3.02, resp)." (PMID 26295053, 2015). "When considering GST family genes, EPHX1 Tyr113His and XPD C156A together, we found that the higher the polymorphism number among these genes, the higher the risk for skin cancer development." (PMID 26295053, 2015). "EPHX1 is also a member of another enriched pathway, the metabolism of DMBA; DMBA is a widely used chemical compound to induce skin cancer in animal models." (PMID 32858528, 2020). "In conclusion, GSTs, EPHX1, and XPD are potential genetic factors for arsenic-induced skin cancers." (PMID 26295053, 2015).
brain tumors (1 paper, 2013). "The parental smoking-childhood brain tumor association was quite different for maternal vs. paternal smoking, overall and by strata of genotype for EPHX1 H139R and mEH activity." (PMID 24260161, 2013). "A positive association between hours per day of exposure to paternal smoking during pregnancy and childhood brain tumor risk was observed only among children with a high-risk genotype (HR or RR) for EPHX1 H139R (Pinteraction = 0.07)." (PMID 24260161, 2013). "However, interaction ORs for childhood brain tumors, EPHX1 H139R and parental smoking were above null for both maternal smoking and paternal smoking." (PMID 24260161, 2013).
Cirrhosis (1 paper, 2021). A chronic disorder of the liver in which liver tissue becomes scarred and is partially replaced by regenerative nodules and fibrotic tissue resulting in loss of liver function. "For mild cirrhosis,median abundance was significantly lower than the control for onlyfour proteins: CES1 (by 47%, p = 0.003*), FMO3 (by37%, p < 0.001**), EPHX1 (by 41%, p = 0.005*), MGST3 (by 51%, p = 0.003*), MRP2 (54%, p < 0.001**), and OATP1B1 (by 54%, p < 0.001**)." (PMID 34428046, 2021).
congenital malformations (1 paper, 2010). "EPHX1 polymorphisms may be associated with the pharmacokinetics of carbamazepine and the risk of phenytoin-induced congenital malformations." (PMID 27713373, 2010).
Immunodeficiency (1 paper, 2024). Failure of the immune system to protect the body adequately from infection, due to the absence or insufficiency of some component process or substance. "Therefore, this study proposed that EIF4EBP1 and EPHX1 contribute to immunodeficiency and further affect the prognostic survival status of AML patients by negatively modulating the infiltration level of CD8 T cells and γδT cells." (PMID 39300580, 2024).
inflammatory bowel disease (1 paper, 2025). A spectrum of small and large bowel inflammatory diseases of unknown etiology. "EPHX1 (microsomal epoxide hydrolase) functionally depends on cg03138928 EPHX1_E152_F, associated with inflammatory bowel disease." (PMID 40111834, 2025).
lung adenocarcinoma (1 paper, 2009). A carcinoma that arises from the lung and is characterized by the presence of malignant glandular epithelial cells. "The other two SNPs were EPHX1 rs1051741, in medium LD with EPHX1 rs2234922, and EPHX1 rs2292568, nominally significantly associated with risk of lung adenocarcinoma in our data." (PMID 19479063, 2009).
lymphoma (1 paper, 2013). A malignant (clonal) proliferation of B- lymphocytes or T- lymphocytes which involves the lymph nodes, bone marrow and/or extranodal sites. "We have studied the prevalence of three functional polymorphisms affecting these genes rs1051740 EPHX1, rs1800566 NQO1 and rs662 PON1 in 215 patients with lymphoma and 214 healthy controls." (PMID 23651475, 2013). "We found that rs1051740 or rs1800566 in EPHX1 and NQO1 were not related with lymphoma susceptibility as previously reported by others." (PMID 23651475, 2013). "This analysis revealed that the combination of the PON1, EPHX1 and NQO1 polymorphisms did not increase the lymphoma risk associated with the PON1 polymorphism alone (OR = 1.7 vs. 1.5)." (PMID 23651475, 2013).
mental disorder (1 paper, 2020). A disease that has its basis in the disruption of mental process. "In addition, Ephx1 and several other genes (Pla2r1, Zmym6, Trappc9, and Nqo2) are annotated in the RGD as genes associated with neurodegenerative diseases and/or mental disorders." (PMID 32429546, 2020). "Furthermore, Ephx1 correlates with neurodegenerative diseases and mental disorders and accordingly can be considered one of the most likely candidate genes responsible for the relation between elevated blood pressure and the signs of neurodegeneration during aging." (PMID 32429546, 2020).
Nephropathy (1 paper, 2014). A nonspecific term referring to disease or damage of the kidneys. "Epoxide hydrolase 1– the product of Ephx1 (increased 3.6 fold) – is protective of nephropathy via its EET arachidonic acid metabolites." (PMID 24827579, 2014).
nicotine dependence (1 paper, 2025). Physical and psychological dependence on nicotine. "Among the genetic determinants, polymorphisms in the CHRNA3/5 and EPHX1 genes have been implicated in nicotine dependence and susceptibility to COPD in several populations." (PMID 41301874, 2025). "With the current sample (TI ≤ 40, n = 76; TI > 40, n = 47; Controls, n = 29; COPD, n = 94), the minimal detectable absolute differences to achieve 80% power were ~25 percentage points for CHRNA3–nicotine dependence contrasts and ~11 percentage points for EPHX1–COPD." (PMID 41301874, 2025).
pancreatic cancer (1 paper, 2025). "By preventing TRIM21‐mediated ubiquitination and subsequent degradation of EPHX1, Bezafibrate sensitizes pancreatic cancer cells to gemcitabine, offering a novel and promising therapeutic strategy." (PMID 39739616, 2025). "More importantly, we demonstrated that inhibiting the interaction between TRIM21 and EPHX1 with Bezafibrate significantly sensitized pancreatic cancer cells to gemcitabine." (PMID 39739616, 2025). "Given the critical role of TRIM21 in pancreatic cancer, we conducted a small molecule drug screening using lipid modifying agents to target the binding domain between TRIM21 and EPHX1." (PMID 39739616, 2025). "Initially, we observed that EPHX1 overexpression (EPHX1‐OE) reduced pancreatic cancer cell proliferation, while EPHX1 knockout (EPHX1‐KO) promoted proliferation, without affecting pancreatic cancer metastasis." (PMID 39739616, 2025).
pancreatic disease (1 paper, 2021). "Other studies revealed an association between pancreatic disease and allelic variants of the EPHX1 (epoxide hydrolase 1), DSP (desmoplakin), HLA-DQA1, and HLA-DQB1 (major histocompatibility complex) genes." (PMID 34945117, 2021).
cancer (23 papers, 2003 to 2026). A tumor composed of atypical neoplastic, often pleomorphic cells that invade other tissues. "While EPHX1 is well-studied regarding cancer risk, few studies have explored its relationship with CIN." (PMID 40526606, 2025). "We showed that the eGFR baseline cutoff <90 ml/min/1.73m2 and TC genotype of EPHX1 rs1051740 were significantly associated with an increased risk of cisplatin-induced AKD among cancer patients." (PMID 40526606, 2025). "Our association analysis results show EPHX1 rs1051740 heterozygous genotype to be associated with AKD in our combined three-cancer-type cohort." (PMID 40526606, 2025). "According to reports, the presence of EPHX1 gene polymorphisms has been linked to the susceptibility of different types of cancers." (PMID 37965333, 2023). "EPHX1 is an enzyme that aids in the detoxification of cigarette-related chemicals, which is a significant risk factor for the development of certain cancers." (PMID 34209243, 2021). "In this meta-analysis, 99 eligible case–control studies including 39,528 cases and 54,685 controls were included to provide a comprehensive assessment of the relationship between EPHX1 polymorphisms and cancer risk." (PMID 25261893, 2014). "Odds ratios (ORs) with 95% confidence intervals (CIs) were calculated to assess the strength of the association between EPHX1 polymorphisms and cancer risk." (PMID 25261893, 2014). "Over the past two decades, a number of studies have been conducted to investigate the relationship between EPHX1 polymorphisms and cancer in different populations." (PMID 25261893, 2014). "Since that date, several more studies have emerged to assess the relationship between the Tyr113His and/or His139Arg polymorphisms of the EPHX1 gene and susceptibility to a variety of cancers." (PMID 25261893, 2014). "The findings from some previous studies suggested that genetic polymorphism in EPHX1 has important roles in the development of cancers." (PMID 25261893, 2014). "This meta-analysis was performed to derive a more precise estimation of relationship between two EPHX1 polymorphisms and risk of different types of cancer." (PMID 25261893, 2014). "In some studies, EPHX1 high-activity alleles have been associated with increased risk of various types of cancer." (PMID 24455257, 2013). "According to several studies, an increased risk of cancer is associated with lower activity of the His/His protein product; nevertheless, EPHX1 high-activity alleles have been associated with an increased risk for various types of cancer." (PMID 24455257, 2013). "The present meta-analysis provides the most comprehensive and up-to-date evidence on putative EPHX1 enzyme activity predicted from two genetic polymorphisms, Y113H and H139R, and risk of developing cancers." (PMID 21445251, 2011). "Certainly, the actual EPHX1 enzyme activity should be measured in cancer case-control population to confirm cancer susceptibility of EPHX1 activity." (PMID 21445251, 2011). "In the present study, both meta-regression and subgroup analysis by ethnicity revealed that ethnicity is a source of heterogeneity and have a major influence on the cancer risk of these two EPHX1 polymorphisms." (PMID 21445251, 2011). "Consequently, EPHX1 inhibition is thought to be rather deleterious, since it increases the toxicity of xenobiotics, as well as the risk of cancer and inflammatory diseases." (PMID 33374956, 2020). "Given the known differential effect of EPHX1 alleles in the detoxification of procarcinogens, it has been proposed that the two functional polymorphisms may affect cancer risk." (PMID 22928041, 2012). "The associations of each of EPHX1 Y113H and H139R polymorphisms with cancer risk were analyzed." (PMID 21445251, 2011). "Given the known differential effect of EPHX1 alleles in the detoxification of procarcinogens, it has been proposed that these polymorphisms may affect cancer risk." (PMID 21445251, 2011).